SMARCB1 (SWI/SNF related BAF chromatin remodeling complex subunit B1)
Diseases named in the same sentence as SMARCB1 in open-access papers (continued):
Sharing a sentence is not in itself a finding about the gene and the disease.
tumor (continued). "Rhabdoid tumours (RTs) are highly aggressive tumours of infancy, frequently localized in the central nervous system (CNS) where they are termed atypical teratoid/rhabdoid tumours (AT/RTs) and characterized by bi-allelic inactivation of the SMARCB1 tumour suppressor gene." (PMID 26818002, 2016). "The mechanisms by which SMARCB1 loss contributes to tumor progression are not fully understood, and analyses of genes regulated by SMARCB1 have revealed several candidate oncogenes, including components of the cell cycle machinery, sonic hedgehog pathway, and canonical Wnt signaling." (PMID 27783942, 2016). "The allele frequency of the SMARCB1 mutation in mRNA seq data was 75%, also supporting the loss of the wild type allele and the consequently biallelic inactivation of SMARCB1 in the tumour (but as in exome data not reaching a frequency of 100% due to some nontumor cells contamination)." (PMID 26998479, 2015). "In the present case, loss of the healthy SMARCB1 allele in the tumour led to biallelic inactivation of the gene that is reflected by the increased allele frequency of the germline mutation in the tumour compared to blood and by the negative IHC staining for SMARCB1 protein." (PMID 26998479, 2015). "Collectively, copy number losses of critical genes involved in chromatin remodeling, especially SMARCB1 and ATRX, were observed in UTROSCTs with extrauterine metastasis, suggesting an important mechanism for tumor evolution and progression." (PMID 41317331, 2026). "Given the inherent commonality of their biology (i.e. biallelic inactivation of SMARCB1 or more rarely SMARCA4) the therapeutic approach should be similar for intra-cranial and extra-cranial tumours." (PMID 41680284, 2026). "Concurrently, SNF5 (SMARCB1), a core SWI/SNF subunit regulating proliferation‐apoptosis balance, demonstrates tumour‐suppressive functions in HCC." (PMID 41578412, 2026). "The tumor cells showed expression of PAX8, CA9, AMACR/P504S, Vimentin, CK7, CD10, FH, INI1(SMARCB1) and ELOC(TCEB1), and ELOC was mainly located in the nucleus." (PMID 41306531, 2025). "SMARCB1 (also known as INI-1), a core subunit of the SWI/SNF chromatin remodelling complex, functions as a tumour suppressor." (PMID 39925590, 2025). "Tumor xenograft assays demonstrated resistance to EGFR-TKI-afatinib in the shSMARCB1 group, with a notable increase in tumor size upon SMARCB1 silencing." (PMID 39971779, 2025). "These tumor suppressor genes found on chromosome 22, near the NF2 region, include SMARCB1 and LZTR1." (PMID 40337438, 2025). "In rhabdoid tumor cells, DNA methylation is decreased and PRC2 members are concomitantly released from the p16 locus upon SMARCB1 re-expression, also suggesting an interplay between PRC2, SWI/SNF, and DNA methylation." (PMID 38499326, 2024). "We found that STAT3 KD reduced tumor growth and lung metastasis compared with STAT3 control in SMARCB1 KO BLCA tumors." (PMID 38355560, 2024). "Mosaic expression for SMARCB1 (NKSCC—33%; KSCC—21.9%) and SMARCA4 (NKSCC—14.6%; KSCC—12.2%) was identified, showing an impact on tumor size and progression." (PMID 39590317, 2024). "Since promoting differentiation has anti-tumor effects in CRC, we next sought to characterize if SMARCB1 is a dependency." (PMID 38472198, 2024). "SMARCB1/INI1 is one of the core subunit proteins of the ATP-dependent SWI/SNF chromatin remodeling complex and it has an important tumor suppressor action." (PMID 37176098, 2023).
tumor (continued). "For example, SMARCB1 is downregulated in AML because of repressive methylation of the CpG islands in its promoter, compared to non-tumor hematopoietic cells." (PMID 36810086, 2023). "To address these issues, we integrated data from single-cell (sc)RNA sequencing of human tumours, multi-region RNA sequencing, bulk transcriptomic data from 2 RMC cohorts, and SMARCB1 gain of function experiments in cellular models." (PMID 37236926, 2023). "In conclusion, our study demonstrates that SMARCB1 is a key regulator of the renal enhancer program, which defines the context in which PAX8 is required for tumor growth." (PMID 37554444, 2023). "We observed a second somatic hit in SMARCB1 in all tumor specimens via LOH of chr22, inclusive of the SMARCB1 gene region." (PMID 35912263, 2022). "While traditionally viewed as a tumour suppressor gene in the context of rhabdoid tumours and EPS, targeting of retained SMARCB1 merits functional investigation." (PMID 35839307, 2022). "The BAF complexes/SMARCB1, Menin, and KMT2D all share additional roles in their inhibition of canonical Wnt signaling, thereby acting in a tumor-suppressive manner." (PMID 36969744, 2022). "It was later shown in 1998 that biallelic alterations to SMARCB1 were present in the vast majority of MRT cases (90%), consistent with the recessive “two-hit” tumor suppressor model of oncogenesis." (PMID 35892904, 2022). "SMARCB1/INI-1 (also known as BAF47) is a core subunit of the SWI/SNF complex, and acts as a tumor suppressor by regulating gene transcription and cell proliferation." (PMID 36431263, 2022). "In the development of this tumour type, a chromosomal translocation involving BAF subunit SS18 leads to the formation of an SS18-SSX fusion protein that displaces SMARCB1 in the BAF complex." (PMID 33941852, 2021). "In our clinical case SMARCB1 was not mutated in the germline DNA and the partial deletion of chromosome 22 not involving the SMARCB1 gene, nevertheless the immunohistochemistry of the AT/RT tumor of our patient demonstrated the absence of the SMARCB1 protein, suggesting the loss of both alleles." (PMID 34777208, 2021). "By analysing the expression of five subunits of the SWI/SNF complex (INI1/SMARCB1, SMARCA2, SMARCA4, ARID1A, PBRM1), we further explored the relevance of alterations in chromatin remodelling in glandular differentiated tumours." (PMID 32198650, 2020). "SMARCB1/INI1 and key proteins in a variety of pathways, such as polycomb pathway, the p16-RB pathway, sonic hedgehog, and WNT signaling pathway, connected with tumor proliferation and progression." (PMID 32420340, 2020). "We also found clonal indels in NF2 in two tumors (cdRCC and mixRCC), and MET (mixRCC), SMARCB1 (pRCC1) and ROS1 (pRCC2) indels in one tumor each." (PMID 32555180, 2020). "(c) Glycerol gradients (10–30%) followed by SDS-PAGE analysis of rhabdoid tumor cell line G401, as compared to SMARCB1 wild-type cell line HA1E, show ARID1A is seen in higher fractions when SMARCB1 is expressed (left)." (PMID 30860482, 2019). "Chromosome 22q contains several known tumor suppressors, such as NF2, CHEK2 and SMARCB1, and all the three tumor suppressors were deleted in the three cases." (PMID 28177878, 2017).
tumor (continued). "FISH analysis showed that SMARCB1/INI1 was deleted, and most of the tumor cells had a male gonosomal complement with an X (green) and a Y (red) chromosome, which was consistent with donor origin." (PMID 29258531, 2017). "Loss of SWI/SNF function has been associated with malignant transformation, and recent data demonstrate that several components of the SWI/SNF complexes, including ARID1A, ARID2, SMARCA4 (BRG1), SMARCB1 (SNF5), and PBRM1, function as tumor suppressors." (PMID 27351279, 2016). ", SMARCB1 and SMARCA4) as tumor repressors, emerging evidence suggests that SWI/SNF activity is essential for tumor initiation, maintenance and progression." (PMID 27495308, 2016). "The SMARCB1 gene, located at 22q11, codes for BAF47, a core subunit of the SWI/SNF ATP-dependent chromatin remodeling complex and acts as a tumor suppressor gene." (PMID 26347853, 2015). "SMARCB1 is a subunit of the ATP-dependent chromatin remodeling complex SWI/SNF, a powerful epigenetic tumor suppressor, which directly antagonizes the histone methyltransferase EZH2." (PMID 24983247, 2014). "Our findings suggest that SMARCB1/INI1 and genetic hot spots mapping to the long arm of chromosome 22 play an important role in tumor metastatic spreading." (PMID 24286138, 2013). "INI1 is a 385 amino acid, 44 kDa nuclear protein (also called hSNF5, BAF47 and SMARCB1) component of the SWI/SNF chromatin remodeling complex that is involved in tumor suppression." (PMID 21994574, 2009). "Fourteen tumor samples from these nine patients were analysed by comparative genomic hybridization (CGH) and molecular analysis for SMARCB1 (hSNF5/INI1)." (PMID 18509505, 2008). "Next-generation sequencing (NGS) analysis revealed copy number loss of SMARCB1 and a novel GSTT1::IGLC7 fusion in the tumor, while no other gene rearrangements, including those involving EWSR1, NR4A3, or FUS, were detected." (PMID 42052495, 2026). "In patients with RTPS1, tumours develop at an earlier age than in patients without germline SMARCB1 PVs." (PMID 40794298, 2025). "Immunohistochemically, SMARCB1/INI1 staining is negative in tumor cells, which can lead to a diagnosis of AT/RT." (PMID 40291196, 2025). "This mosaic pattern results from mixed immuno-positive and -negative nuclei, consistent with the expression of the SMARCB1 protein in a subset of tumour cells." (PMID 40794298, 2025). "SMARCB1, part of the SWI/SNF chromatin remodeling complex, functions as a tumor suppressor." (PMID 40761980, 2025). "Meanwhile, SMARCB1 deletion led to the upregulation of the IL6/JAK/STAT3 signaling pathway, which activated the transcriptional activity of STAT3 and enhanced the proliferative and invasive abilities of tumor cells." (PMID 39995416, 2025). "Additionally, in this case, tumor cells don’t express CD117, TFE3, HMB45, or SDHB, but express FH and INI1(SMARCB1)." (PMID 41306531, 2025). "The SMARCB1 and LZTR1 genes are involved in the regulation of cell growth and tumor suppression." (PMID 40764996, 2025). "One central observation of our single-cell analyses of human and murine SMARCB1-negative PTCL was the extensive network of tumor-TME interactions." (PMID 39362842, 2024). "Having recently demonstrated mammalian SWItch/sucrose nonfermentable roles in translation, we assessed SMARCB1 potential roles in translation in rhabdoid tumor cells." (PMID 39542244, 2024). "Treatment of SMARCB1 KO (clone C16) xenografts with TTI-101 showed a significant decrease in BLI signal compared to the vehicle control, indicative of decreased tumor growth." (PMID 38355560, 2024). "We first revealed by cell viability assays that rhabdoid tumor cells’ sensitivity to homoharringtonine were dependent on the absence of SMARCB1." (PMID 39542244, 2024). "This tumor is associated with tumor-specific translocations involving the Ewing’s Sarcoma (EWS) gene and not infrequently with SMARCB1 mutations." (PMID 37446319, 2023).
tumor (continued). "This tumor is molecularly characterized by a complete lack of SMARCB1 expression, identified as loss of INI1 immunohistochemical stain in 90% of cases." (PMID 37446319, 2023). "Areas of tumour formation or cellular hyperproliferation, as found in Smarcb1-negative ATRT models, are not detectable." (PMID 37219662, 2023). "Most patients died of the disease within 6 months, although one case with SMARCB1-negative rhabdoid carcinoma in the cecum without tumor recurrence 48 months after surgery has been reported." (PMID 36732357, 2023). "He met clinical criteria for NF2 from his tumor types and underwent germline genetic testing using a saliva sample for NF1, NF2, LZTR1, and SMARCB1, which did not demonstrate any mutations." (PMID 38058737, 2023). "Indeed, EZH2 inhibition by EPZ-6438 induced apoptosis in SMARCB1-mutant MRT cells and dose-dependent tumor regression in xenograft-bearing mice." (PMID 36900330, 2023). "Multiple studies have reported that ATRT patients who retained positive nuclear staining for SMARCB1 in tumour cells lacked staining for SMARCA4." (PMID 37433987, 2023). "In contrast, no tumour formation was detected in Smarcb11148del/1148del mice and in IHC stainings, all cells were SMARCB1-positive." (PMID 37219662, 2023). "Additional clinical studies of ICI therapy for SMARCB1-negative colorectal rhabdoid carcinoma are required to establish a therapeutic strategy for this type of tumor." (PMID 36732357, 2023). "Similarly, while OXPHOS was increased upon SMARCB1 expression in cell lines, it was reduced in RMC tumours." (PMID 37236926, 2023). "Tumor growth in vivo was totally abrogated by PAX8 KD (P81Ctrl(A)), partially rescued for P81Ctrl(LT) cells and completely rescued for P81S11(LT) cells, which were transduced with the more efficient SMARCB1 sgRNA." (PMID 37554444, 2023). "SMARCB1 is a core subunit of the SWI/SNF complex and functions as a tumour suppressor gene." (PMID 37433987, 2023). "Different from the original primary tumor, cell line TCS627 demonstrated loss of SMARCA4 and SMARCA2 in a very large majority of cells, while SMARCB1 expression was completely absent." (PMID 38201285, 2023). "Two out of sixteen patients with synchronous tumors had no detectable GLM; one of them presented in tumor tissue only a homogenous deletion of SMARCB1." (PMID 35565313, 2022). "By comparing gene expression of Smarcb1-negative tumor clusters (TCs) of all three MYC subtypes, we identified localization-specific tumor markers." (PMID 35318328, 2022). "The tumor cells were characteristically negative for SMARCB1/INI1 expression, which was however positive in vascular endothelial cells as an internal staining control." (PMID 35804041, 2022). "Even though both ATRT-SHH and MYC tumors arise from Smarcb1-negative Sox2-positive precursor cells, Sox2 expression levels in the tumor itself vary between the tumor subgroups of both murine and human samples." (PMID 35318328, 2022). "Immunohistochemical analysis indicated a metastatic lung tumor derived from the SNUC revealed completely negative SMARCB1 expression in the nuclei of the tumor cells." (PMID 33959255, 2021). "Several subunits of the SWI/SNF complex including SNF5 (SMARCB1/INI1/BAF47), ARID1A (BAF240A), SMARCA4 (BRG1), ARID1B (BAF250B), ARID2 (BAF200) and PBRM1 (BAF180) exert critical tumor suppression activities, through inhibiting oncogenic transcription, cell cycle, epigenetic instability and etc.." (PMID 33670012, 2021). "Rhabdoid tumours, albeit the majority being AT/RT, only developed in these mice when Smarcb1 was inactivated during very early embryogenesis, but not at later fetal stages or in adult animals." (PMID 33658498, 2021). "INI1/SMARCB1/hSNF5/BAF47 is an invariant component of the SWI/SNF chromatin remodeling complex, involved in a multitude of cellular functions, including transcription, cell cycle regulation, development, and tumor suppression." (PMID 33980829, 2021).
tumor (continued). "Intriguingly, expression of WT SMARCB1 considerably increased adhesion and spreading, restoring a quasi-normal cell morphology, whereas the tumor-derived mutant M4 and, to a lower extent, M3 did not exert this effect." (PMID 33024572, 2020). "SWI/SNF (SWItch/Sucrose Non-Fermentable), a chromatin remodeling complex mainly including the components ARID1A, SMARCA4, SMARCB1, SMARCD1, and ACTL6A, is considered a tumor suppressor, and inactivation of SWI/SNF subunits is thought to drive tumorigenesis by altering gene expression." (PMID 31590683, 2019). "In both tumor samples, no deletion of SMARCB1 gene was detected by FISH, indicating that the loss of the INI1 protein was due to either SMARCB1 gene mutation or epigenetic modification." (PMID 31331120, 2019). "Each of these tumor cell lines expressed the epithelial marker, CAM5.2, and lacked expression of SMARCB1 similar to that observed in the primary tumor." (PMID 30860482, 2019). "Another CRC study has reported low expression of SMARCB1 to associate with poor differentiation, liver metastasis, and poorer survival regardless of the MMR status or tumor stage." (PMID 30108113, 2018). "Our findings imply that a large tumor‐specific deletion had occurred on the chromosome 22 not harboring the germline SMARCB1 deletion of exons 8–9." (PMID 29779243, 2018). "In this study, we report the follow‐up of a patient (II.4) with a germline SMARCB1 deletion of exons 8–9 who survived an AT/RT treated at the age of 2 years without tumor recurrence as determined by analysis of the patient at the age of 17 years." (PMID 29779243, 2018). "This mosaic pattern results from mixed immuno-positive and -negative nuclei, consistent with the expression of SMARCB1 in a subset of tumour cells." (PMID 27921248, 2017). "Smarcb1 negative cell islets were also occasionally found in lungs and kidneys, but we did not observe any tumour in the CNS." (PMID 26818002, 2016). "A recent case report from Italy illustrates an INI1(+) AT/RT case in a 9-month-old boy whose tumor showed retained INI1/SMARCB1 expression by IHC and lacked genetic alterations in the INI1 gene." (PMID 26109171, 2015). "In a recent study, RMC tumor specimens were noted to have an absence of SMARCB1/INI1 by immunohistochemistry." (PMID 25215253, 2014). "RTK is a highly aggressive tumor occurring in young children, has a dismal outcome, and is characterized by pathological rhabdoid features and molecular biallelic inactivation of the SMARCB1 (hSNF5/INI1) gene." (PMID 23638012, 2013). "The most striking finding of our study is the association between loss of SMARCB1/INI1 expression and a worse clinical outcome, regardless of the tumor stage and MMR status." (PMID 24286138, 2013). "SMARCB1/INI1-negative immunostaining showed a significant relation with poor differentiation, presence of liver metastasis and advanced tumor stage IV." (PMID 24286138, 2013). "Overall these data demonstrate that several HDAC are highly expressed in SMARCB1 negative primary tumors and tumor cell lines." (PMID 23764045, 2013). "Central pathology re-evaluation of primary tumor revealed negative SMARCB1/INI1 staining, prompting a reassessment of the original diagnosis to ATRT." (PMID 23510391, 2013). "INI1 (hSNF5, BAF47, SMARCB1) is a tumor suppressor biallelically deleted in RTs." (PMID 21951911, 2011). "In most cases (37/43 genes), methylation was more frequent in cell lines than primary tumours, however for 6 genes this pattern was reversed (ZNF215: 21% and 42% respectively, DAPK1: 4% and 39%, EPHA3 13% and 32%, SMARCB1: 8% and 27%, EPS8 4% and 21% and MCM2: 0% and 21%)." (PMID 19493342, 2009).